IL6 (interleukin 6)
Diseases named in the same sentence as IL6 in open-access papers (continued):
Sharing a sentence is not in itself a finding about the gene and the disease.
oral squamous cell carcinoma (90 papers, 2010 to 2026). "In oral squamous cell carcinoma, the increase in IL-6 levels is associated with enhanced invasiveness, while suppression of IL-6 enhances the chemosensitivity and radiosensitivity of cancer cells." (PMID 40643463, 2025). "However, further in vitro and in vivo studies are needed to clarify the association between IL-6 expression in oral squamous cell carcinoma and the production of PTHrP and G-CSF." (PMID 27316348, 2016). "The present study examined the immunohistochemical expression for interleukin-6 (IL-6), a pleiotropic inflammatory cytokine, in oral squamous cell carcinoma (OSCC) to elucidate the association of IL-6 expression with tumor progression, chemoresistance and prognosis." (PMID 25761055, 2015). "Moreover, the serum level of IL-6 showed a high diagnostic sensitivity of nearly 95% in patients with oral cavity SCC." (PMID 26082902, 2015). "Relative to high IL6-producing cells (3000 pg/106 cells, human oral squamous cell carcinoma), the premalignant and malignant lung cell lines used in our study only produced negligible levels of IL6." (PMID 41304808, 2025). "Researchers studied several salivary protein biomarkers that can be used for the detection of oral squamous cell carcinomas, such as Interleukin-6 (IL-6), Interleukin-8 (IL-8), and tumor necrosis factor-alpha (TNF-α), to name a few." (PMID 40096419, 2025). "In oral squamous cell carcinoma (OSCC), high levels of TAM-derived IL-6, promote EMT and enhance the expression of genes associated with stemness, via the IL-6/STAT3/thrombospondin 1 (THBS1) signaling pathway." (PMID 39981232, 2025). "Research investigated Interleukin-6 (IL-6) levels in oral fluid of patients with Oral Squamous Cell Carcinoma (OSCC) together withevaluation about how clinical staging affected these levels." (PMID 40978585, 2025). "Salivary interleukin-6 (IL-6) demonstrates strong potential as a non-invasive biomarker forthe diagnosis and prognostication of oral squamous cell carcinoma, effectively distinguishing it from potentially malignant disordersand healthy individuals." (PMID 40978585, 2025). "While prior studies have implicated extracellular ENO1 in CD14-dependent TLR4 signaling in monocytes and a paracrine ENO1/TLR4/IL-6 axis driving metastasis in oral squamous cell carcinoma, its direct interaction with TLR4 in GBM remained unexplored." (PMID 41353343, 2025). "The concentrations of TNF-α, IL-8, and IL-6 in human saliva and serum progressively increased from healthy individuals to oral leukoplakia patients and finally to oral squamous cell carcinoma (OSCC) patients (P < 0.05)." (PMID 41415031, 2025). "It has been established that salivary IL-6 can be used as a biomarker for the detection of oral squamous cell carcinoma." (PMID 40096419, 2025). "Elevated serum IL-6 concentrations have been detected in OSCC (Oral Squamous Cell Carcinomas), resulting in larger tumor size, nodal metastases, and poorer patient survival." (PMID 38519574, 2024). "It has been shown that cancer occurs in the pancreas due to increased IL-6 production, which promotes the growth and invasion of oral squamous cell carcinoma." (PMID 39336457, 2024). "There were 9 primary clusters of co-cited references, including oral squamous cell carcinoma, tissue microarray, cancer immunity, biomarkers, monocytes, interleukin-6, m1, and immune checkpoint pathway." (PMID 38115315, 2023). "In oral squamous cell carcinoma cells, blocking NF-κB activation reduced ROS production, which was reversed by exogenous IL-6 treatment." (PMID 38139043, 2023). "A recent study also reported that interleukin-6 (IL-6) and interleukin-8 (IL-8) are candidate markers for oral squamous cell carcinoma." (PMID 35626430, 2022).
oral squamous cell carcinoma (continued). "Several studies reported that salivary IL-6 concentrations are significantly increased in patients with oral and oropharyngeal diseases, and higher IL-6 expression is inversely related to prognosis and survival of patients with oral squamous cell carcinomas." (PMID 36555876, 2022). "ALDH3A1 acts as a prognostic biomarker and inhibits the epithelial–mesenchymal transition of oral squamous cell carcinoma through IL-6/STAT3 signaling pathway." (PMID 34928471, 2022). "In a previous study, high IGFBP-3 expression improved the survival rate of patients with oral squamous cell carcinoma, achieved through NF- κB/IL-6/ROS signalling to promote radiosensitivity." (PMID 35069971, 2022). "The purpose of this study was to examine the effects of orento on TLR-mediated IL-6 production by PAMP stimulation in oral squamous cell carcinoma." (PMID 36614140, 2022). "The results showed that the presence of oral squamous cell carcinoma influenced the salivary levels of IL-8, IL-6, VEGF, and IL-1β, determining an increased concentration." (PMID 32899735, 2020). "In HNSCC and oral squamous cell carcinoma, serum levels of IL-6 are significantly higher than control patients and serum IL-6 is a potential biomarker for these cancers." (PMID 31226168, 2019). "Salivary IL-6 mRNA was previously identified as a promising biomarker of oral squamous cell carcinoma (OSCC)." (PMID 31766212, 2019). "Here, we investigated the diagnostic potential of serum immunoglobulin G antibody against periodontal pathogens, P. gingivalis and F. nucleatum, and serum IL-6 for oral squamous cell carcinoma (OSCC)." (PMID 31167516, 2019). "IL6 is regarded as a tumor-promoting cytokine in diverse kinds of cancer including oral squamous cell carcinoma (OSCC) 32-35." (PMID 31692996, 2019). "Key words:NF-κB, IL-6, immunohistochemistry, oral squamous cell carcinoma, oral precancerous lesion." (PMID 26595830, 2016). "Increased expression of IL-6 immunoreactivity in oral squamous cell carcinoma was more frequently observed in patients with advanced stage, cervical lymph node metastasis, or distant metastasis." (PMID 27034885, 2016). "The average serum IL-6 level in patients with oral cavity SCC was 5.8 pg/ml compared with the much lower value of 0.2 pg/ml in the control group (P<0.001)." (PMID 26082902, 2015). "In one study, the effects of stress-related hormones on interleukin-6 (IL-6) secretion and proliferation of oral squamous cell carcinoma (OSCC) cells was investigated." (PMID 25048798, 2014). "Consistent with the protumor role of chronic inflammation, interleukin (IL)-1 beta, IL-6, and IL-8 expressed in oral potentially malignant disorders (OPMDs) increase when the latter evolve into oral squamous cells carcinoma (OSCC) and, even more, when OSCC metastasizes." (PMID 40805215, 2025). "Therefore, it is of interest to evaluate interleukin-6 in oral squamous cell carcinoma as a salivary biomarker." (PMID 40978585, 2025). "Interleukin-6 (IL-6) has been reported to be critical in oral squamous cell carcinoma (OSCC)." (PMID 35513871, 2022). "Moreover, IL6 signaling promotes the invasion and metastasis of oral squamous cell carcinoma via the activation of integrin β1." (PMID 35008304, 2021). "They acknowledged IL-6 as a determining biomarker in oral cavity SCC." (PMID 26082902, 2015). "The current study greatly supports the increase of IL-6 in oral cavity SCC." (PMID 26082902, 2015). "Moreover, in vitro experiments revealed that IL-6 induces VEGF-C expression in human oral squamous cell carcinoma cell line and VEGF-C expression in IL-6 treated murine LECs." (PMID 25254213, 2014). "IL-6 could promote proliferation via JAK2/STAT3/SOX4 pathway in oral squamous cell carcinoma cells." (PMID 39963655, 2024).
oral squamous cell carcinoma (continued). "In patients with oral squamous cell carcinoma (OSCC) and oropharyngeal squamous cell carcinoma (OPSCC), there was a significant decrease in neopterin and IL‐6 levels in saliva following the surgical removal of the malignancy." (PMID 40831233, 2025). "Therefore, we chose IL-6 as a candidate for demonstrating the detection of proteins since the goal of this study is to inch us closer to the point-of-care detection of oral squamous cell carcinoma, although the system may be adapted for any protein of interest." (PMID 40096419, 2025). "In oral squamous cell carcinoma, RACK1 decreased IL-6, CCL5, and CSF levels and increased the M2/M1 ratio in an NF-κB axis-dependent manner." (PMID 38315284, 2024). "In the context of oral squamous cell carcinoma (OSCC), CAFs-released IL-6 and GM-CSF drive the activation of M2-like TAMs in the TME." (PMID 37821959, 2023). "The inflammatory interleukins-6 and -8 (IL-6 and IL-8) produced in vitro by LPA-stimulated oral squamous cell carcinoma (OSCC) promoted osteoclastogenesis and bone resorption." (PMID 37373424, 2023). "The expression of IL‐6 and STAT3 in 116 patients with oral squamous cell carcinoma (OSCC) were independent, and only high IL‐6 expression significantly promoted vascular invasion and decreased the 5‐year disease‐free survival rate." (PMID 35356799, 2022). "Serum IL-6 was evaluated in 42 erosive OLP (EOLP) patients and 10 normal mucosa and 10 oral squamous cell carcinoma cases using ELISA technique." (PMID 26535093, 2015). "For example, a significant correlation between IL-6 protein and VEGF-C mRNA with lymph node metastasis in human oral squamous cell carcinoma has been demonstrated." (PMID 25254213, 2014). "For example, interleukin-6 (IL-6)-mediated signaling can regulate VEGF-C expression via the PI3K-Akt pathway, leading to lymphangiogenesis in human oral squamous cell carcinoma." (PMID 23344023, 2012). "Many cancer types, including oral squamous cell carcinoma, exhibit constitutive expression of CCL2 and IL-6, whereas normal oral mucosal epithelial cells express lower levels of these cytokines and chemokines." (PMID 24213108, 2011). "In addition, PLOD2 activated integrin β1 through IL-6/STAT3 signaling to promote invasion and metastasis in oral squamous cell carcinoma." (PMID 38184566, 2024). "Key words:Salivary cytokines, IL-6, IL-8, TNF-α, oral squamous cell carcinoma, diagnosis." (PMID 37099710, 2023). "In oral squamous cell carcinoma cell line CAL27, orento significantly inhibited periodontopathogenic bacterium Porphyromonas gingivalis lipopolysaccharide (LPS) and lipoproteins (PAMP)-stimulated production of interleukin (IL)-6." (PMID 36614140, 2022). "A study reported another mechanism that IL-6/STAT3 pathway could be activated through ALDH3A1, contributing to reduced cell proliferation, migration, and invasion in oral squamous cell carcinoma 28, which was in consistent with our findings." (PMID 34234849, 2021). "IL-6 could also regulate VEGF-C at mRNA level through Akt/mTOR signaling pathway, which effectively decreased the lymphangiogenesis and metastasis in oral squamous cell carcinoma." (PMID 25884175, 2015).
emphysema (89 papers, 2007 to 2025). "This emphysema aggravation as a result of antibiotic exposure was associated with increased levels of inflammatory cells, IL-6, IFNγ and protein concentrations in bronchoalveolar lavage fluid." (PMID 37779147, 2023). "It has been well established that high levels of IL-6 and IL-8 are strongly associated with the progression of airflow obstruction and the severity of emphysema." (PMID 35280870, 2022). "Increases in IFNγ- and IL-6-producing blood T cells to elastin fragments had a positive association with the annual rate of emphysema progression in active smokers." (PMID 34271910, 2021). "The IL-6 association with emphysema progression was also seen in subgroup analysis which included only subjects without COPD or chronic bronchitis and no emphysema at baseline." (PMID 29065892, 2017). "IL-6 was associated with progressive airflow obstruction over 5 years and both IL-6 and IL-8 were associated with progressive emphysema over 5 years." (PMID 29065892, 2017). "In particular, emphysema defined by parenchymal voxels with computed attenuation values less than −950 Hounsfield Units (HU) was associated with higher blood levels of IL-6 and MMP-7, but lower TNFα levels." (PMID 23577098, 2013). "These mediators are implicated in emphysema, and we demonstrate that treatment with IL-6 neutralizing antibodies is associated with decreased expression of MMPs and TIMP-1." (PMID 21799929, 2011). "Whether IL-6, previously associated with progression of emphysema, would further improve the model should be examined." (PMID 28610627, 2017). "Classic IL-6 signaling through membrane-bound IL-6R has been associated with regenerative activities, whereas trans-signaling has been related to proinflammatory activities and blocking trans-signaling in an emphysema mouse model, where it suppressed alveolar cell apoptosis." (PMID 38302925, 2024). "IL-6 could promote the development of pulmonary emphysema associated with apoptosis in mice." (PMID 25814921, 2015). "Biologics targeting upstream alarmins (e.g., IL-33/TSLP) and downstream cytokines (e.g., IL-1β, IL-6) aim to disrupt inflammatory redundancy; cell-based and regenerative approaches represent long-term precision strategies for emphysema." (PMID 41024111, 2025). "Reduced osteoclast numbers, lower RANKL expression, and decreased expression of IL-1β and IL-6, protecting against emphysema in KO mice." (PMID 40248692, 2025). "In a study of mice exposed to cigarette smoke, a high fiber diet decreased interleukin-6 and interferon-gamma in bronchoalveolar lavage and serum samples, attenuated development of emphysema, and was protective against alveolar destruction." (PMID 38468283, 2024). "SCFA administration restored emphysema development with reduced inflammatory cells, IL-6, and IFNγ and decreased LC3B, atg3, and atg7 levels." (PMID 37779147, 2023). "This is in agreement with our previous demonstration of BCX’s ability to decrease tobacco-specific carcinogens and nicotine-driven IL-6 mRNA expression and emphysema in the lung." (PMID 36771049, 2023). "MTMR14 overexpression inhibited lung inflammation and reduced levels of IL-6 and KC in bronchoalveolar lavage fluid, as well as prevented emphysema and a decline in lung function." (PMID 35035670, 2022). "The levels of interleukin-6 (IL-6) and interferon-γ (IFN-γ) were significantly increased in the BALF and serum of the emphysema group, which is presumably associated with increased macrophage infiltration." (PMID 33772084, 2021). "The increase or imbalance of the IL-6 expression is strongly implicated in the development of COPD, associated with progressive airflow obstruction and emphysema." (PMID 35058774, 2021). "PM significantly increased mice emphysema and airway inflammation measured by mean linear intercept, alveolar destroy index and total cell, neutrophil counts, cytokines IL-6, tumor necrosis factor (TNF)-α, CXCL1, IL-1β in bronchoalveolar lavage fluid." (PMID 32116706, 2020).
emphysema (continued). "Recent studies targeted the NALP1 inflammasome, IL-6, and chemotactic protein in efforts to significantly reduce inflammation in brain injury, myocardiac infarction, and pulmonary emphysema, respectively." (PMID 32486412, 2020). "The levels of the cytokines IL-6 and IFN-γ were increased in the BALF and serum of emphysema mice, presumably in association with increased macrophage infiltration." (PMID 32681029, 2020). "Another study showed that levels of TNF-α, IL-6, and IL-1β increased in sputum during emphysema in humans." (PMID 32963734, 2020). "The COPDGene study is one of the largest current and former smoker cohorts with long term CT follow up and this study is one of the first to report IL-6 as an independent biomarker of emphysema progression." (PMID 29065892, 2017). "Third, IL-6 is associated with cardiovascular disease in COPD patients and recent literature supports a vascular etiology of emphysema." (PMID 29065892, 2017). "Another strong association was between IL-6 and COPD affection status, airflow limitation and emphysema progression." (PMID 29065892, 2017). "This is potentially concordant with recent experimental evidence that suggests the role of IL-6 trans-signaling in the development of emphysema occurs independently of inflammatory processes, although replication of the results is needed." (PMID 28334838, 2017). "Tumor necrose factor (TNF) –α, interferon-γ and various classes of interleukins as the IL-1β, IL-6, IL-8, IL-10, IL-17, IL-18, IL-32 and others are involved in the progression of emphysema." (PMID 27775634, 2016). "The important role of IL-6 in the pathogenesis of emphysema was further suggested by clinical studies demonstrating the elevated systemic IL-6 concentrations in patients with emphysema." (PMID 25814921, 2015). "Specifically, we found that inhaled nCB induces the production of IL-1β and IL-6, two pro-inflammatory cytokines that are required for mDC-mediated differentiation of Th17 cells and emphysema development." (PMID 26437452, 2015). "More recently, using gp130F/F mice homozygous for a subtle knock-in mutation in gp130 that deregulates intracellular signalling by the IL-6 cytokine family, we found that gp130F/F mice spontaneously develop emphysema by age 6 months." (PMID 24144354, 2014). "Experimental studies have shown that IL-6 overexpression in the murine lung results in emphysema-like airspace enlargement and airway inflammation." (PMID 23866260, 2013). "Another study demonstrated diminished levels of the pro-inflammatory cytokines TNFα, interleukin-1, interleukin-6 and interleukin-8 in rat pulmonary tissue following bosentan treatment of induced emphysema." (PMID 24342001, 2013). "We developed a dual cytokine enzyme-linked immunocell spot assay, the γ-6 Spot, using CD4 T cell IFN-γ and IL-6 responses and found that it discriminated emphysema with 90% sensitivity." (PMID 22969766, 2012). "Three of the 33 inflammatory markers, IL-6, MMP-7 and tumor necrosis factor alpha (TNF-α), were associated with quantitative emphysema." (PMID 19718453, 2009). "While IL-6 and MMP-7 were directly associated with F-950, TNF-α was inversely related to emphysema severity." (PMID 19718453, 2009). "For instance, incorporating inflammatory markers (e.g., C-reactive protein and interleukin-6) or imaging modalities (e.g., CT-based emphysema quantification) could provide a more comprehensive understanding of disease progression and comorbidities." (PMID 39949428, 2025). "IL-6, which is primarily secreted by macrophages, has neutrophil chemotactic effects and is associated with COPD severity, the rate of decline in lung functions, and emphysema progression as assessed by CT scans." (PMID 35401244, 2022). "The adverse effect of IL-6 on the lung was further supported by a study that showed that elevated IL-6 could in part account for the development of emphysema through IL-6 trans-signaling-mediated apoptosis of ATII." (PMID 34211985, 2021).